TNF (tumor necrosis factor)
Diseases named in the same sentence as TNF in open-access papers (continued):
Sharing a sentence is not in itself a finding about the gene and the disease.
Anxiety (continued). "However, conditional deletion of TNF from microglia using CX3CR1-Cre prevented the increase in anxiety-like behavior in stressed CX3CR1-Cre positive mice relative to their unstressed CX3CR1-Cre expressing littermates, although there was a baseline behavioural shift in these animals." (PMID 36104437, 2022). "This was dependent on TNF signaling within the ventral hippocampus, as local injection of DN-TNF bilaterally into the ventral hippocampus was sufficient to block the expression of stress-induced anxiety-like behavior relative to littermates injected with saline." (PMID 36104437, 2022). "Furthermore, high TNF-α (P<0.001, adjusted P <0.001) and increased IL-17 (P=0.014, adjusted P=0.056), but not IL-1β (P=0.648, adjusted P=1.000) or IL-6 (P=0.131, adjusted P=0.524), were correlated with increased anxiety severity grade." (PMID 35239774, 2022). "In addition, clinical and basic studies have proven that microglial activation as well as proinflammatory cytokines, such as TNF‐α and IL‐6, arising from both peripheral and CNS induced by infection or stress response was involved in the development of anxiety‐like behaviors." (PMID 35977050, 2022). "Interestingly, blocking TNF-α signaling improves anxiety and depressive-like behaviors." (PMID 36386232, 2022). "Interestingly, the presence of the rare allele of these SNPs would confer a differential effect on the anxiety levels among these patients, suggesting that these SNPs may have different effects on the functions of TNF-α." (PMID 35528795, 2022). "Minocycline also blocked PTSD fear and anxiety-like behaviors shortly after systemic and intra-hippocampal administration, suggesting that the inflammatory mediator(s) mediating those actions, such as TNF-α, were produced in the hippocampus as well as peripherally." (PMID 34512420, 2021). "Certainly, any of the psychosocial dimensions of anxiety can develop into chronic stress if not addressed; Preparation for Labor and Relationship with Spouse/Partner were of particular interest due to their association with IL-6/IL-10 and TNF-α/IL-10 ratios." (PMID 34360332, 2021). "Consequently, drugs that reduce TNF-α synthesis may reduce pain, anxiety and depressive symptoms by moderating TNF-α-induced changes in neurotransmission." (PMID 34512420, 2021). "Unfortunately, the trigger for development of PTSD and co-morbid pain symptoms is unknown, but findings by us and others using the single prolonged stress (SPS) model of PTSD suggest that tumor necrosis factor-α (TNF-α) initiates the development of pain and anxiety-like behaviors." (PMID 34512420, 2021). "Interestingly, decreases in hippocampal TNF and IL-6 levels were observed in a murine eCM model with cannabidiol treatment, which also increased brain derived neurotrophic factor levels, promoted eCM survival and prevented post-CM anxiety-like behaviours." (PMID 32703204, 2020). "Inflammatory signalling, such as increased brain-cortical TNF levels in conjunction with either increased IL-6 or IL-1β, and alterations in growth factor levels, e.g. brain derived neurotrophic factor and neuregulin, can contribute to the development of anxiety in eCM and behavioural sequelae." (PMID 32703204, 2020). "In the SNL and the TNFα hippocampal injected mice, our results gave solid evidence that the hippocampal activation of microglia alone is responsible for the damages to the plasticity of hippocampal pyramidal neurons, and further the induction of the nociceptive, depressive and anxiety behaviors." (PMID 30115941, 2018). "The cytokine tumour necrosis factor-α (TNF-α) and its closely associated janus kinase 2 (JAK2)-signal transducer and activator of transcription (STAT3) signalling pathway regulate the neuro-inflammatory response in the brain, thus participating in the development of anxiety." (PMID 28336920, 2017).
Anxiety (continued). "Therefore, research on the inhibitory effects of anti-anxiety drugs on the TNF-α/JAK-STAT pathway could reveal the targets or mechanisms of action of these drugs." (PMID 28336920, 2017). "For example, injection of TNF-α into the ventricles causes elevations in mean arterial pressure and repeated microinjections of TNF-α and Ccl2 into the amygdala prior to prolonged alcohol exposure have been associated with an exaggerated anxiety-like response during withdrawal." (PMID 22626265, 2012). "The results show a significant correlation between anxiety behavioral indicators and CORT levels, inflammatory factors (IL-6, IL-1β, CD86, TNF-α, TGF-β, IL-10), 5-HT, and GABA." (PMID 40078708, 2025). "Studies have shown that the experimental administration of tumor necrosis factor alpha (TNF-α), interleukin-1 beta (IL-1β), and IL-6 results in a depressive effect, including anxiety, drowsiness, and fatigue, in humans." (PMID 40746874, 2025). "These cells release cytokines and chemokines, such as TNF-α, IL-1β, IFN-γ, IL-6, iNOS, etc., which ultimately lead to neuronal death and trigger anxiety." (PMID 39905541, 2025). "PS-MPs induced anxiety through activation of the PERK-NF-κB signaling pathway, mediated by HRAS, in microglia, with increased pro-inflammatory cytokines TNFα and IL-1β." (PMID 41303677, 2025). "Our findings suggest that solanesol inhibits neuro-inflammation by decreasing the TIA1 level to reduce IL-1β and TNF-α expression, meanwhile inhibiting microglial and astrocytic activation in the ACC and ultimately ameliorating anxiety-like behaviors in mice." (PMID 39337650, 2024). "The hippocampus displays microglial activation, elevated IL-6 and tumor necrosis factor alpha (TNF-α), as well as neurotrophic factor signaling disturbances in APP1/PS1 mice with anxiety-like phenotypes." (PMID 39703925, 2024). "From the perspective of the mechanism of sugar on anxiety, on the one hand, sugar intake may participate in the neuroinflammatory process in brain regions by changing the levels of inflammatory factors such as IL-6, TNF-α, leptin, and iNO, leading to excessive production of nitric oxide." (PMID 39479195, 2024). "Our findings consistently reveal that TNF-α, secreted by CD8+ T cells, inhibits neurogenesis and induces anxiety-like behaviour." (PMID 39386089, 2024). "At the end of the study, HFFD resulted in anxiety‐like behavior, reduced locomotor activity, neuroinflammation (increased brain GFAP, IL‐6, MCP‐1, IFN‐γ, TNF‐α), and systemic inflammation (increased plasma GFAP, IFN‐γ, TNF‐α, IL‐12p70, reduced plasma IL‐10)." (PMID 39619979, 2024). "In P301S mice with anxiety-like phenotypes, inflammation markers appear to differ between sexes: males express more monokines induced by interferon gamma (MIG), TNF-α, IL-13, and IL-10 than females." (PMID 39703925, 2024). "ROS induces the production of TNF-α and IL-1β by activating the NFkBp65-COX2-mPGES-1 signaling pathway, thus accelerating anxiety." (PMID 37273529, 2023). "TNF-α and IL-1 production is aided by mPGES-1, which functions in conjunction with COX-2 to trigger anxiety." (PMID 37273529, 2023). "Consistent with previous studies, we also observed that LPS markedly increased the expression of TNF-α, IL-Iβ, and IL-6 in the PFC and peripheral serum, inducing depressive-like and anxiety-like behaviors." (PMID 35573384, 2022). "Similar results were found in a group of stressed adults where the administration of Lactobacillus plantarum P8 led to a decrease in anxiety accompanied by a reduction of pro-inflammatory cytokines such as interferon (IFN)-γ and tumor necrosis factor (TNF)-α." (PMID 35295092, 2022). "BHB was also effective in reducing anxiety behaviors in rodent models of PTSD and restoring serum TNF-α levels that were elevated in response to single prolonged stress." (PMID 35927237, 2022).
Anxiety (continued). "At the same time, it can help reduce NE in the brain, CORT and TNF-α in the serum, and then inhibit the hyperactivity of the HPA axis and reduce anxiety." (PMID 35458204, 2022). "The evidence from human studies shows a close relationship between prenatal exposure to pro-inflammatory cytokines, such as TNF-α, IL-1β, IL-6, IL-17a, and ASD, schizophrenia, anxiety, depression, and ADHD." (PMID 35937892, 2022). "Consistent with our findings, TNF can directly increase AMPAR content at CA1 hippocampal synapses and increased output from the ventral hippocampus can drive anxiety-like behavior." (PMID 36104437, 2022). "Blood inflammatory cytokines, e.g., IL-1, IL-6, and tumor necrosis factor (TNF), their specific receptors, and acute phase reagents such as C-reactive protein (CRP), were increased in patients with anxiety." (PMID 33920547, 2021). "ANOVA results of anxiety-like behaviors from THL and anti-TNF-α antibody treatment studies using EPM." (PMID 34512420, 2021). "We previously reported on preliminary studies that prior to appearance of anxiety-like behaviors at day 9, allodynia was evident as early as 3 days post-SPS, and was accompanied by elevated serum TNF-α levels in SPS-treated rats." (PMID 34512420, 2021). "Repeated saline injections led to anxiety-like behaviour in the OFT and NSFT, increased M/Ms activation and reduced TNF-α serum levels, corticosterone reactivity and hippocampal neuroplasticity." (PMID 34279714, 2021). "Reduced hyperalgesia and/or anxiety behaviors following SPS correlated with reduced circulating and hippocampal TNF-α and other inflammatory cytokines 1–2 weeks post-SPS." (PMID 34512420, 2021). "In a recent preclinical study, mice exposed to chronic unpredictable stress exhibited elevated levels of TNFα within the HPC and increased depressive- and anxiety-like behaviors, which were attenuated by minocycline treatment." (PMID 33935636, 2021). "In our present study, both peripheral and central IL-1β, IL-6, and TNF-α levels were significantly increased after CFA injection, and the injected mice showed obvious anxiety-like behaviors." (PMID 32019580, 2020). "In a previous mouse study, social defeat stress-induced microglial activation released tumor necrosis factor-α (TNF-α), leading to neuronal changes in the prefrontal cortex (PFC) and behavioral changes (anxiety)." (PMID 32522975, 2020). "When TNFα was also knocked-down at the same time as S1PR3, the increase in anxiety-like behavior was reversed but IL1β knock-down with knock-down of S1PR3 did not produce behavioral changes different from S1PR3 knock-down alone." (PMID 31316053, 2019). "A useful step in understanding its mechanism further would be to experimentally compare preemptive use of dexmedetomidine and one of the specific anti-TNF biologicals reported to minimize POCD delirium, pain and anxiety, and to induce morphine tolerance." (PMID 29725287, 2018). "In the present study, we confirmed that early treadmill exercise improved anxiety‐like behavior and learning and memory and induced decreases in glial cells and proinflammatory cytokines (PAF, IL‐6, TNF‐α, ICAM, and VCAM) activation." (PMID 29201553, 2017). "The abnormality rates of IL-6, IL-8, TNF-α and CRP in both the BD group and the atypical BD group were all significantly higher than those in the simple anxiety group (P < 0.05)." (PMID 29065864, 2017). "Sera TNF-α levels were increased in SLE patients with depressive symptoms (p < 0.001) and with anxiety symptoms (p = 0.014)." (PMID 26732584, 2016). "An increase in inflammatory markers such as IL-1, IL-6, TNF-alpha, and IFN-gamma have been documented in ADs including PTSD, PD, and OCD as well as anxiety-related personality traits such as neuroticism." (PMID 25390645, 2014).
Anxiety (continued). "Therefore, to determine whether chronic PS, a model we have shown increases the basal expression of TNF, could also elicit behavioral deficits in disorders mediated by inflammation, depressive- and anxiety-like behaviors were assessed and compared to the CUS model." (PMID 22248083, 2012). "And microglia-secreted TNF-α impairs the trafficking of AMPA receptors to neuronal membranes, reducing synaptic transmission efficiency in circuits mediating mood regulation and ultimately leading to anxiety-like behaviors." (PMID 41294833, 2025). "In the present study, the proinflammatory cytokines IL‐6 and TNF‐α affected both emotions and anxiety, but unlike the anti‐inflammatory cytokines IL‐10 and ADPN, they were not related to physical disease severity." (PMID 40700022, 2025). "Similarly, TNF-α influences the hypothalamic–pituitary–adrenal (HPA) axis, promoting dysregulation that exacerbates the physiological and psychological symptoms of anxiety." (PMID 40218134, 2025). "4‐AP may be effective in reducing anxiety‐like behavior in sleep‐deprived mice by modifying the levels of NMDA‐R, AMPA‐R, and TNF‐α, while simultaneously reducing oxidative stress induced by sleep deprivation in the hippocampus." (PMID 40059459, 2025). "4‐AP may be effective in attenuating anxiety‐like behavior in sleep‐deprived mice by modifying the levels of NMDA‐R and AMPA‐R and TNF‐α and simultaneously reducing oxidative stress in the hippocampus." (PMID 40059459, 2025). "Our findings are supported by a previous study demonstrating that AGOM treatment decreased the release of cytokines (TNF-α, IL-6 and IL-1β) and restored BDNF levels and the activity of the antioxidant enzymes CAT and GPx in the brain in an HFD-induced anxiety-like behavior model." (PMID 40076566, 2025). "Using a moderated multiple mediation model, we found preliminary evidence that TNFα, cortisol, and anxiety, but not fibrinogen, mediate this relationship." (PMID 40650919, 2025). "In contrast, the intervention group with FD but without anxiety had significant reductions in IL-6 and TNF-α (p < 0.05), along with a significant decrease in the PAGI-SYM score (p < 0.001)." (PMID 40606168, 2025). "Here, we aimed to determine whether solanesol can reduce IL-1β and TNF-α levels by regulating TIA1 in the ACC, thereby improving anxiety-like behaviors in mice." (PMID 39337650, 2024). "Western blot analysis revealed that CFA-induced upregulation of the levels of pro-inflammatory cytokines interleukin (IL)-1β and tumor necrosis factor α (TNF-α), which played crucial roles in regulating anxiety, returned to normal in the anterior cingulate cortex (ACC) after solanesol treatment." (PMID 39337650, 2024). "This study hypothesized that anxiety and/or curcumin could significantly influence cortisol and systemic inflammatory cytokine levels in patients with moderate anxiety (MCP-1, sCD14, TNF alpha)." (PMID 39334711, 2024). "Using TNF-α deficient mouse model (which do not produce TNF-α), we further validate that HBV vaccination had no inhibitory effects on the hippocampal neurogenesis and anxiety-like behaviour." (PMID 39386089, 2024). "TNFα mice did not exhibit signs of sickness behavior, or reduced locomotor/exploratory activity, and stereotypical/anxiety-like behaviors in the open-field test, which are typically associated with systemically induced inflammation." (PMID 38891027, 2024). "On the other hand, quercetin inhibited nicotine-triggered CPP reinstatement, alleviated METH-induced anxiety-like behavior in mice, attenuated the activation of astrocytes, and reduced the levels of IL-1beta and TNF-α, but not IL-6." (PMID 37112606, 2023). "We found that treatment with TNFα antibody at PD16.5 not only rescued autistic-like behaviors, including anxiety, and repetitive and social behaviors in PE-exposed offspring, but also deficits in the developmental spines on pyramidal neurons in the cortex and hippocampus." (PMID 37290815, 2023).
Anxiety (continued). "Secondly, direct infusion of TNF-α into the PrL induced anxiety-like behaviors without influencing the pain threshold." (PMID 36917193, 2023). "IL1β, TNFα and IL6 were evaluated in the medial prefrontal cortex, nucleus acumens and amygdala, structures known to play pivotal roles in motivational, social or anxiety behavioral processes." (PMID 36675275, 2023). "Among the highly myopic patients, the levels of MIP-1β and TNF-α were significantly higher in those with anxiety than those with no anxiety (all P < 0.05)." (PMID 37699875, 2023). "In this line, the levels of IL-6 and TNF-α, two major pro-inflammatory cytokines, have shown to be noticeably related to the severity of anxiety." (PMID 35949300, 2022). "Mice lacking TNF also did not have the normal anxiety-induced increase in latency to enter the light compartment and decrease in transitions between the compartments." (PMID 36104437, 2022). "The results of the present study indicated that the level of BDNF, a neurobiological marker for anxiety, was increased in response to CLB treatment, which had an anxiolytic effect on behaviors and decreased the level of TNF‐α in the hippocampus in winning mice." (PMID 34878231, 2022). "Other cytokines may also be released by activated microglia, and there is evidence that IL1 contributes to stress induced anxiety-like behavior, although the observed increase in IL1 was more transient than the increase in TNF." (PMID 36104437, 2022). "As TNF-α can produce hyperalgesia, increase anxiety-like behaviors and increase N/OFQ expression, we hypothesized that blockade of the TNF-α surge would prevent or reduce the TNF-α increases and symptoms noted following exposure to SPS." (PMID 34512420, 2021). "Since TNF-α can increase N/OFQ mRNA and peptide, we posited that increased TNF-α with SPS leads to increased synthesis and release of N/OFQ that contributes to SPS-induced allodynia, hyperalgesia and anxiety-like behaviors." (PMID 34512420, 2021). "A single injection of anti-TNF-α antibody to male and female rats during the SPS procedure prevented the development of allodynia, hyperalgesia, and elevated serum N/OFQ, and reduced SPS-induced anxiety-like behaviors in males." (PMID 34512420, 2021). "The alcohol-induced neuroinflammation may also contribute to the anxiety-like behavior as higher basal levels of TNFα and MCP-1 were observed in patients with anxiety." (PMID 33767622, 2021). "Since acute THL treatment prevented SPS-induced increases in serum TNF-α, nociceptive sensitivity and modulated NOP receptor and peptide mRNA, its effect on the development of anxiety-like behaviors was assessed in Veh-, THL-, SPS-, and SPS+THL-treated rats using the EPM test." (PMID 34512420, 2021). "Similarly, increased levels of inflammatory cytokines, such as tumor necrosis factor-α (TNF-α), IL-1, and IL-6, can diminish positive mood and induce anxiety." (PMID 31581672, 2019). "Animal studies have found that COX-2 inhibition attenuates neuroinflammation (hippocampal inflammatory markers cytokines IL-1β, TNF-α, and brain PGE2 levels) and circulating corticosterone, and may also alleviate symptoms of anxiety and cognitive decline." (PMID 31671812, 2019). "In our correlational analyses, a negative association was observed between IL‐6 and TNF‐α levels and time spent in open arm and exploration time of central regions and indicated that proinflammatory cytokines may be involved in the pathophysiology of anxiety‐like behavior." (PMID 29201553, 2017). "Peripheral administration of LPS induces inflammatory cytokines such as tumor necrosis factor (TNF) α, interleukin (IL)-1β, IL-6 which may produce depressive or anxiety-like behavior." (PMID 29228944, 2017).